SZT2 (SZT2 subunit of KICSTOR complex)
Description:
As part of the KICSTOR complex functions in the amino acid-sensing branch of the TORC1 signaling pathway. Recruits, in an amino acid-independent manner, the GATOR1 complex to the lysosomal membranes and allows its interaction with GATOR2 and the RAG GTPases. Functions upstream of the RAG GTPases and is required to negatively regulate mTORC1 signaling in absence of amino acids. In absence of the KICSTOR complex mTORC1 is constitutively localized to the lysosome and activated. The KICSTOR complex is also probably involved in the regulation of mTORC1 by glucose. May play a role in the cellular response to oxidative stress (By similarity).
Synonyms: C1orf84; KIAA0467; FLJ10387; SZT2B; RP11-506B15.1; FLJ34502; SZT2A; KICS1; DEE18; EIEE18
Tractability: PROTAC: ubiquitination databases record sites on it; its protein half-life has been measured.
Gene: Protein-coding gene on chromosome 1 (43,389,882 to 43,454,247, forward strand). Ensembl gene ENSG00000198198.
Subcellular location: Lysosome membrane; Peroxisome
Subcellular location (Human Protein Atlas): Actin filaments; Nucleoplasm; Vesicles
Pathways (Reactome):
Cellular responses to stimuli: Amino acids regulate mTORC1
Gene Ontology:
Molecular function: protein binding
Biological process: cellular response to amino acid starvation; cellular response to glucose starvation; corpus callosum morphogenesis; negative regulation of TORC1 signaling; protein localization to lysosome; central nervous system development; post-embryonic development; regulation of superoxide dismutase activity; response to nutrient levels
Cellular component: GATOR1 complex; GATOR2 complex; KICSTOR complex; lysosomal membrane; peroxisome
Genetic constraint (gnomAD): Loss-of-function variants: 216 observed, 415.59 expected, observed/expected ratio (o/e) 0.52, 90% interval 0.46 to 0.58. The upper end of that interval is the gene's LOEUF score, 0.58, which puts it in group 2 of 6, group 1 being the genes least tolerant of losing a copy. Missense variants: 3,857 observed, 4,606.2 expected, observed/expected ratio (o/e) 0.84, 90% interval 0.81 to 0.86. Synonymous variants: 1,693 observed, 1,812.2 expected, observed/expected ratio (o/e) 0.93, 90% interval 0.9 to 0.97.
Gene-disease validity (ClinGen):
ClinGen rates the evidence that SZT2 causes each of these diseases.
genetic developmental and epileptic encephalopathy (autosomal recessive): Definitive. A complex neurodevelopmental disorder characterized by a range of developmental delays and epileptic encephalopathy phenotypes.
Homologues: Orthologues: chimpanzee SZT2 (99% identical), macaque SZT2 (98% identical), dog SZT2 (94% identical), rabbit SZT2 (93% identical), guinea pig SZT2 (92% identical), mouse Szt2 (92% identical), rat Szt2 (92% identical), pig SZT2 (92% identical), tropical clawed frog szt2 (59% identical), Caenorhabditis elegans F54B3.1 (18% identical).
Diseases named in the same sentence as SZT2 in open-access papers:
SZT2 is named in the same sentence as 30 diseases in open-access papers, as found by Europe PMC text mining. Sharing a sentence is not in itself a finding about the gene and the disease. The quoted sentences say what the papers report.
epilepsy (15 papers, 2019 to 2025). A brain disorder characterized by episodes of abnormally increased neuronal discharge resulting in transient episodes of sensory or motor neurological dysfunction, or psychic dysfunction. "The exact role of SZT2 in epilepsy is still under investigation, but mutations in this gene have been implicated in various forms of epilepsy." (PMID 39024300, 2024). "SZT2 variants were identified in six unrelated cases with heterogeneous epilepsy, including one de novo null variant and five pairs of biallelic variants." (PMID 37213690, 2023). "In this study, we identified novel SZT2 variants in six unrelated patients with heterogeneous epilepsy, including one de novo null variant and five pairs of biallelic variants." (PMID 37213690, 2023). "LOF of SZT2 causes overactivation of mTORC1 signaling, which is one of the hallmarks of epilepsy and brain malformations." (PMID 37213690, 2023). "A total of 11 SZT2 variants were identified in six unrelated patients with heterogeneous epilepsy, including DEE in the patients with null variants and partial epilepsy in the patients with compound heterozygous missense variants." (PMID 37213690, 2023). "SZT2 was initially identified in mice with epilepsy, and recurrent mutations of SZT2 are also reported in patients with epilepsy." (PMID 36250465, 2022). "Here we report the generation of the first induced pluripotent stem cell (iPSC) lines from a patient with treatment-resistant epilepsy, carrying compound heterozygous mutations in SZT2 (Mut1: c.498G>T and Mut2: c.6553C>T), and his healthy heterozygous parents." (PMID 36361881, 2022). "There is increasing evidence that SZT2 is associated with neurological diseases such as growth retardation and epilepsy." (PMID 31949263, 2020). "Biallelic variations in SZT2 have been demonstrated to cause a characteristic clinical entity with epilepsy, developmental delay, macrocephaly and a dysmorphic corpus callosum." (PMID 31430354, 2019). "In combination, these data suggest that epilepsy and developmental delay are the core symptoms of patients with SZT2 mutations." (PMID 31397114, 2019). "The Szt2 gene appeared to be strongly implicated in seizure threshold in mouse and mutations in its human orthologue (SZT2) may be involved in macrocephaly, developmental delay, pharmacoresistant epilepsy and intellectual disability phenotypes." (PMID 34573345, 2021). "Szt2 was originally identified in mice only a decade ago, and its function was there correlated with epilepsy." (PMID 36361881, 2022). "There have been increasing number of reports of SZT2-related neurological diseases, the main symptoms of which are epilepsy, developmental delay, macrocephaly and a dysmorphic corpus callosum." (PMID 31430354, 2019). "SZT2 was also reported in two Saudi sisters with epilepsy, developmental delay, and macrocephaly." (PMID 37628333, 2023). "In this respect, it has been considered that SZT2 variants cause a broad phenotypic spectrum from epileptic encephalopathy and severe developmental delay to mild intellectual disability without epilepsy." (PMID 31430354, 2019). "The phenotypes were largely heterogeneous and formed a continuum of characteristics from early‐onset epileptic encephalopathy to mild ID without epilepsy, which may be associated with the alteration in residual protein function because truncating mutations cause complete loss of SZT2 function." (PMID 31397114, 2019). "While SZT2 and FLNA variants were common in epilepsy, there were no reports regarding photosensitivity." (PMID 36034301, 2022).
Epileptic encephalopathy (8 papers, 2019 to 2023). A condition in which epileptiform abnormalities are believed to contribute to the progressive disturbance in cerebral function. "Our results expand the genotype and phenotypes of SZT2‐related DEEs, suggesting that SZT2 mutations play a role in developmental delay and epileptic encephalopathy, with high susceptibility to SE and relatively specific MRI findings." (PMID 31397114, 2019). "Despite the reports of more than 10 cases of epileptic encephalopathies harboring SZT2 mutations, the clinical features due to SZT2 mutations remain to be elucidated." (PMID 31397114, 2019). "Pathogenic variants in SZT2 are associated with epileptic encephalopathy." (PMID 34816733, 2021). "Overall, the data presented form the basis to comprehensively investigate the physiological functions of SZT2 that could explain major molecular events in the pathophysiology of developmental and epileptic encephalopathy in patients with SZT2 mutations." (PMID 34685691, 2021). "SZT2 mutation‐related cases have also been reported, presenting mainly with heterogeneous phenotypes ranging from mild‐moderate intellectual disabilities (ID) without seizures, to early‐onset epileptic encephalopathy with severe ID." (PMID 31397114, 2019).
developmental delay (5 papers, 2019 to 2023). "A wide spectrum of developmental delay and facial dysmorphism is strongly noted among patients with a mutation in the SZT2 gene." (PMID 37760843, 2023). "The extremely high prevalence of developmental delay amplifies prior studies that suggest an active role for SZT2 in human brain development." (PMID 37760843, 2023).
Intellectual disability (5 papers, 2013 to 2022). "This condition includes behavioral alterations, intellectual disability, poor language development, and seizures, sharing many of the phenotypes observed in patients with pathogenic mutations in SZT2." (PMID 34685691, 2021). "Mutations in the SZT2 gene have been associated with developmental and epileptic encephalopathy-18, a rare severe autosomal recessive neurologic disorder, characterized by psychomotor impairment/intellectual disability, dysmorphic facial features and early onset of refractory seizures." (PMID 36361881, 2022).
developmental and epileptic encephalopathies (3 papers, 2019 to 2023). "In this study, three patients diagnosed with SZT2‐related developmental and epileptic encephalopathies (DEEs) were reviewed aiming to expand knowledge of the genotype and phenotype of SZT2 mutations." (PMID 31397114, 2019).
developmental and epileptic encephalopathy, 18 (2 papers, 2022 to 2023). "Recessive SZT2 variants are reported to be associated with developmental and epileptic encephalopathy 18 (DEE-18) and occasionally neurodevelopment abnormalities (NDD) without seizures." (PMID 37213690, 2023). "Mutations in SZT2 have been associated with developmental and epileptic encephalopathy-18 (DEE18), a rare severe autosomal recessive neurologic disorder." (PMID 36361881, 2022). "In humans, recessive SZT2 variants were reported to be associated with developmental and epileptic encephalopathy 18 (DEE-18, OMIM* 615463) and occasionally NDD without seizures." (PMID 37213690, 2023).
focal epilepsies (2 papers, 2021 to 2023). "However, it is unknown whether the SZT2 variants were associated with partial epilepsy, sharing a similar phenotypic spectrum with other mTOR pathway genes." (PMID 37213690, 2023). "This study suggested that SZT2 variants were potentially associated with partial epilepsy with favorable outcomes without NDD." (PMID 37213690, 2023). "This study identified SZT2 variants in patients that presented mild partial epilepsy with favorable outcomes without NDD, expanding the phenotypic spectrum of SZT2." (PMID 37213690, 2023).
infantile epileptic encephalopathy (2 papers, 2013 to 2021). an epileptic condition characterized by epileptiform abnormalities associated with progressive cerebral dysfunction. "Recently, three mutations in SZT2 were reported in two unrelated children with unexplained infantile epileptic encephalopathy with severe ID." (PMID 24324832, 2013). "While this manuscript was being prepared, three mutations in SZT2 were reported in two unrelated children with unexplained infantile epileptic encephalopathy with severe ID." (PMID 24324832, 2013). "Here, we report a multiplex European American family with non-syndromic ID and application of whole-exome sequencing to identify the responsible gene, SZT2, which was recently reported in two unrelated children with unexplained infantile epileptic encephalopathy with severe ID." (PMID 24324832, 2013).
Macrocephaly (2 papers, 2013 to 2023). Occipitofrontal (head) circumference greater than 97th centile compared to appropriate, age matched, sex-matched normal standards. "Interestingly, all three children had macrocephaly, suggesting that it is a part of the clinical phenotype caused by the SZT2 mutation." (PMID 24324832, 2013). "On the other hand, the unaffected father in our family has macrocephaly and macrocephaly was not present in two children previously reported with SZT2 mutations." (PMID 24324832, 2013).
diabetes (1 paper, 2022). "SZT2 specifically represses mTORC1 during fasting, thus, SZT2-deficiency mimics overnutrition-induced mTORC1 elevation, which is a chronic condition associated with common human diseases, including obesity, diabetes, cancer, and other aging-related diseases." (PMID 36250465, 2022).
Huntington disease (1 paper, 2021). Huntington disease (HD) is a rare neurodegenerative disorder of the central nervous system characterized by unwanted choreatic movements, behavioral and psychiatric disturbances and dementia. "Of note, altered mitophagy equilibrium has been associated with Alzheimer’s and Huntington’s diseases, that were also represented in the SZT2 interactome." (PMID 34685691, 2021).
Hypertension (1 paper, 2018). The presence of chronic increased pressure in the systemic arterial system. "Several novel findings are also highlighted forming the basis for hypotheses meriting further investigation including a potential pleiotropic role of LPR2 in CVD development but also links of SZT2 to hypertension regulation." (PMID 29665821, 2018).
leukemia (1 paper, 2022). A malignant (clonal) hematologic disorder, involving hematopoietic stem cells and characterized by the presence of primitive or atypical myeloid or lymphoid cells in the bone marrow and the blood. "However, unlike mice with inducible deletions of PTEN or TSC1, which developed rapid HSC exhaustion and/or leukemia, SZT2-KO mice survived more than 1 year without obvious abnormalities." (PMID 36250465, 2022).
overnutrition (1 paper, 2022). An imbalanced nutritional status resulting from excessive intake of nutrients. "Thus, SZT2-deficiency is an ideal model to dissect the relationship among overnutrition, mTORC1 hyperactivation, and disease." (PMID 36250465, 2022).
Pancytopenia (1 paper, 2022). An abnormal reduction in numbers of all blood cell types (red blood cells, white blood cells, and platelets). "Ablation of both SZT2 and TSC1 results in rapid HSC exhaustion, pancytopenia, and premature death of mice in a mTORC1-dependent manner." (PMID 36250465, 2022). "Furthermore, ablation of both SZT2 and TSC1 — 2 repressors of mTORC1 on the nutrient and growth factor arms, respectively — led to rapid HSC depletion, pancytopenia, and premature death of the mice." (PMID 36250465, 2022).
neurological diseases (4 papers, 2019 to 2025). "While MED8’s role in neurological diseases has been suggested in preclinical studies, the specific mechanisms and clinical consequences underlying the involvement of SZT2/MED8’s interaction remain areas for further investigation." (PMID 41465117, 2025). "The possible implication of MED8 in neurological diseases has been suggested by its relationship with the Seizure Threshold 2 gene (SZT2) (MIM *615463), whose mutations are related to epileptic encephalopathy and intellectual disability." (PMID 41465117, 2025). "A pathogenic variant in the SZT2 gene could result in hyperactive mTORC1 signaling, which can lead to several neurological disorders." (PMID 37760843, 2023). "Therefore, a SZT2 variant could result in hyperactive mTORC1 signaling and lead to several neurological disorders." (PMID 37760843, 2023).
cancer (2 papers, 2021 to 2022). A tumor composed of atypical neoplastic, often pleomorphic cells that invade other tissues. "SZT2 is part of the KICSTOR complex, which regulates the amino acid-sensing part of the mTORC1 signaling pathway being required for many processes during cell proliferation and survival and often deregulated in cancer." (PMID 34073664, 2021).
neurodevelopmental disorder (2 papers, 2023 to 2025). A behavioral and cognitive disorder with onset during the developmental period that involves impaired or aberrant development of intellectual, motor, or social functions. "Nonetheless, it is frequently reported that agenesis or dysgenesis of the CC among numerous neurodevelopmental disorders as well as in cases of SZT2 mutation." (PMID 37760843, 2023).
SZT2 also shares sentences with these, for which no sentence is quoted: Aymé-Gripp syndrome (1 paper); brain malformations (1); breast carcinoma (1); Kaposi's sarcoma (1); Lissencephaly (1); Obesity (1); polycystic kidneys (1); preeclampsia (1); primary effusion lymphoma (1); retinal degeneration (1); schizophrenia (1); tumor (1).